RN7SL350P (RNA, 7SL, cytoplasmic 350, pseudogene)
Gene: Miscellaneous RNA gene on chromosome 8 (99,613,783 to 99,614,081, reverse strand). Ensembl gene ENSG00000243254.
Homologues: Orthologues: chimpanzee Metazoa_SRP (99% identical), macaque Metazoa_SRP (90% identical). Paralogues in human: RN7SL1 (81% identical), RN7SL2 (81% identical), RN7SL709P (80% identical), RN7SL296P (80% identical), RN7SL3 (79% identical), RN7SL220P (79% identical), RN7SL444P (79% identical), RN7SL478P (79% identical), RN7SL655P (79% identical), RN7SL45P (78% identical), RN7SL664P (78% identical), RN7SL448P (78% identical), and 703 more.